COL4A3 (collagen type IV alpha 3 chain)
Diseases named in the same sentence as COL4A3 in open-access papers (continued):
Sharing a sentence is not in itself a finding about the gene and the disease.
cardiac hypertrophy (2 papers, 2021 to 2022). "Col4a3-deficiency in mice recapitulates multiple features of HF with preserved ejection fraction and is associated with cardiac hypertrophy, diastolic dysfunction, myocardial fibrosis, and mitochondrial dysfunction." (PMID 36005141, 2022). "Similarly, in another genetic mouse model of HF with preserved ejection fraction induced by Col4a3 deficiency, osteopontin deletion was associated with improved parameters of LV diastolic function and cardiac hypertrophy reduction." (PMID 36005141, 2022). "The cardiac hypertrophy phenotype of Col4a3-knockout mice is dependent on the genetic background." (PMID 33416083, 2021).
collagenopathies (2 papers, 2024 to 2025). "Seven families (5.7%) harbored disease-causing variants linked to collagenopathies (2 of the 4 cases with COL4A5 variants were females and 3 families with monoallelic COL4A3 genes)." (PMID 40677324, 2025).
iron deficiency (2 papers, 2022 to 2023). "Supplying Col4a3−/− mice with a low phosphate diet reduced functional iron deficiency and skeletal muscle wasting, factors that were exacerbated in the presence of hyperphosphatemia." (PMID 36966182, 2023). "Low Pi feeding limits functional iron deficiency in Col4a3−/− (Alport ) mice." (PMID 35302487, 2022).
pancreatic cancer (2 papers, 2022). "In this study, we investigated the synergistic effects of juglone and selenium on PANC-1 and BxPC-3 pancreatic cancer cell lines by cell adhesion and invasion assays and evaluation of the mRNA and protein expressions of CDH1, ITGB3 and COL4A3 which play role in metastasis and angiogenesis processes." (PMID 36407358, 2022). "In our study, we did not detect COL4A3 expression at protein level in the PANC-1 and BxPC-3 cell lines, supporting that the earlier study which reported no expression of α3(IV)NC in the pancreatic cancer cells." (PMID 36407358, 2022).
prostate carcinoma (2 papers, 2013 to 2023). A carcinoma that arises from epithelial cells of the prostate gland. "The CC and CT genotype of rs6436661 in the COL4A3 was negatively associated with prostate cancer aggressiveness (OR = 0.74, p-value = 0.040 for CGEMS; OR = 0.71, p-value = 0.034 for Moffitt)." (PMID 23593148, 2013). "Two SNPs (rs10498214 and rs6436661) in the COL4A3 were significantly associated with prostate cancer aggressiveness." (PMID 23593148, 2013). "There were also 5 KLF5K369Q-downregulated and NTZ-upregulated genes whose lower expression levels in human prostate cancers were also significantly associated with worse overall survival, including TMPRSS2, CALB1, SPOCK2, COL4A4, and COL4A3." (PMID 36810084, 2023). "Four SNPs in three genes (COL4A3, PDGFD and ELK3) were associated with prostate cancer aggressiveness in both the CGEMS and Moffitt groups with a p-value less than 0.05." (PMID 23593148, 2013).
Proteinuria (2 papers, 2022 to 2025). Increased levels of protein in the urine. "Proteinuria at presentation was also predictive of variants in COL4A3-5 with detection rates of 37.4% compared to 15% of individuals who did not have proteinuria." (PMID 39349776, 2025). "Proteinuria was present in eight individuals with COL4A3 variants." (PMID 35419377, 2022).
renal dysfunction (2 papers, 2024 to 2025). "Thus, the presence of genetic variants in COL4A3/4/5 should be considered in pregnant women presenting with hematuria, proteinuria, or renal dysfunction." (PMID 38765603, 2024). "Pathogenic variants in the COL4A3, COL4A4, or COL4A5 genes disrupt the proper assembly and structure of collagen type IV, leading to impaired GBM integrity and progressive renal dysfunction, and may also affect ocular and cochlear structures." (PMID 40852417, 2025).
type 1 diabetes (2 papers, 2023 to 2025). "Recent studies in type 1 diabetes (T1D) cohorts have highlighted robust loci such as protective variants in COL4A3 (e.g., rs55703767), as well as signals in AFF3, FRMD3, and the RGMA–MCTP2 region, which are consistently associated with albuminuria, eGFR decline, and ESKD." (PMID 41585789, 2025). "A larger and more recent meta-analysis examining 19,406 individuals of European descent with type 1 diabetes (T1D) identified 16 significant risk loci, showing the strongest association with the missense mutation in the collagen type IV alpha 3 chain (COL4A3) gene." (PMID 36633903, 2023).
age-related macular degeneration (1 paper, 2021). Age-related loss of vision in the central portion of the retina (macula), secondary to retinal degeneration. "Interestingly, single-nucleotide polymorphisms in COL4A3 have been significantly associated with age-related macular degeneration." (PMID 34014299, 2021).
Airway obstruction (1 paper, 2025). Obstruction of conducting airways of the lung. "Interestingly, we also noted a decrease in the same biomarker in patients with airway obstruction, indicating that COL4A3 degradation may play distinct roles in different pathological contexts." (PMID 40760731, 2025).
allergic asthma (1 paper, 2023). A asthma with a basis in a pathological type I hypersensitivity reaction. "In allergic asthma, an increase in the serum level of the COL4A3 degradation marker C4Ma3 is associated with exacerbation of the allergic asthma phenotype, providing a novel biomarker for predicting the response to anti-IgE therapy." (PMID 37841281, 2023).
Alzheimer disease (1 paper, 2023). A progressive, neurodegenerative disease characterized by loss of function and death of nerve cells in several areas of the brain leading to loss of cognitive function such as memory and language. "Pathways associated with Alzheimer’s disease, bladder cancer, endocytosis, lysosomes, and proximal tubule bicarbonate reclamation were significantly elevated in the COL4A3 low-expression subgroup." (PMID 37841281, 2023).
bronchiectasis (1 paper, 2023). Segmental, irreversible dilation of the bronchial tree resulting in the accumulation of secretions which leads to obstruction. "In recent years, novel biomarkers, such as those related to IL-5, IL-33 and COL4A3 are emerging, but their expressions and potential roles in bronchiectasis still await investigation." (PMID 37653511, 2023).
carcinoid (1 paper, 2014). "We also evaluated the expression data of CREB5, PTPRB and COL4A3 from Oncomine, indicating that CREB5, PTPRB and COL4A3 were significantly lower in carcinoid than normal lung tissues, which was accordant to the results of the DASL and RNA-seq datasets." (PMID 25105010, 2014).
cardiomyopathy (1 paper, 2022). A disease of the heart muscle or myocardium proper. "Genes in MCODE 2 (such as TPM4) were significantly involved in cardiomyopathy, and genes in MCODE 4 (such as COL4A3 and COL4A4) were involved in focal adhesion, ECM-receptor interaction, and PI3K-Akt signaling pathway." (PMID 35645614, 2022).
cerebral small vessel disease (1 paper, 2023). Cerebral small vessel disease is the term currently used to pathological processes that affect the brain parenchymal circulation (arterioles, capillaries, and veins). "The COL4A1 gene, in association with COL4A3, are necessary for maturation of type IV collagen, and COL4A1 mutations cause cerebral small vessel disease, i.e., intracerebral hemorrhage and shortened life-span." (PMID 37194065, 2023).
chronic heart failure (1 paper, 2022). "Adrenergic pathways are also implicated in the beneficial effects of SGLT2 inhibitors for patients with chronic heart failure, and may be part of the mechanism of action of cardioprotection by carvedilolin Col4a3-/--129x1/SvJ mice." (PMID 35743114, 2022).
colon cancer (1 paper, 2022). "In colon cancer, the level of collagen expression is the key indicator to predicting the OS and risk, especially the types of COL1A1, COL1A2, COL3A1, COL4A3, and COL4A6." (PMID 36142424, 2022).
COVID-19 (1 paper, 2023). A disease caused by infection with severe acute respiratory syndrome coronavirus 2. "All represented terms showed 5 common genes between our ORF-A549 cells and COVID-19 lung biopsies (COL1A1, COL4A3, COL4A4, COL5A1 and COL11A1)." (PMID 37545510, 2023).
cyst (1 paper, 2025). A sac-like closed membranous structure that may be empty or contain fluid or amorphous material. "According to this study, it is hypothesized that pathogenic variants in COL4A3/COL4A5 that disrupt the type IV collagen α3α4α5 network may result in weakened basement membranes in the distal tubule, making them more susceptible to cyst formation." (PMID 40565535, 2025).
Down syndrome (1 paper, 2025). "In Down syndrome, the overexpression of genes located on chromosome 21—particularly those involved in angiogenesis inhibition, such as COL4A3, endostatin (COL18A1), and RCAN1—is known to contribute to vascular immaturity, pulmonary hypoplasia, and increased risk for pulmonary hypertension." (PMID 41462807, 2025).
gestational diabetes (1 paper, 2024). Carbohydrate intolerance first diagnosed during pregnancy. "Differing from T1DM, neither study up to this current research has identified a connection between variants of TYK2 and COL4A3 genes and the likelihood of developing gestational diabetes." (PMID 38926794, 2024).
glioblastoma (1 paper, 2025). The most malignant astrocytic tumor (WHO grade IV). "By comparing the expression level in different histological types of gliomas, COL4A1 and COL4A2 were better predictors of glioblastoma (AUC = 0.918 and 0.9), followed by COL4A3 and COL4A4 (AUC = 0.67 and 0.746)." (PMID 40351420, 2025).
glioma (1 paper, 2025). A benign or malignant brain and spinal cord tumor that arises from glial cells (astrocytes, oligodendrocytes, ependymal cells). "We found the high expressions in COL4A1 and COL4A2 were positively related to a worse prognosis of glioma patient, while, in COL4A3 and COL4A4 were predicted to a better prognosis." (PMID 40351420, 2025). "It indicated the COL4A1-2 were corelated to a worse prognosis, and COL4A3-4 predicted a better outcome in glioma." (PMID 40351420, 2025). "However, COL4A1-2 and COL4A3-4 have completely opposite effects on glioma patient prognosis, which verified our hypothesis to a certain extent." (PMID 40351420, 2025). "Thus, this part of results further confirmed the COL4A1-2 were positively related to glioma progress, while COL4A3-4 have a negative effect on glioma development." (PMID 40351420, 2025).
heart failure (1 paper, 2022). Inability of the heart to pump blood at an adequate rate to meet tissue metabolic requirements. "Our group recently reported that Col4a3-/--129J mice reproduce multiple features of heart failure with preserved ejection fraction (HFpEF), including symptoms of systemic hypertension and pulmonary congestion." (PMID 35743114, 2022). "male Col4a3-/- 129x1/SvJ mice displayed alterations consistent with heart failure with preserved ejection fraction (HFpEF)." (PMID 35743114, 2022).
liver cysts (1 paper, 2024). "Of note, 4 patients in the COL4A3 cohort had liver cysts and despite no potentially pathogenic variants being found in genes associated with polycystic liver disease (PRKCSH, SEC63, and LRP5), we cannot completely rule out the presence of a second variant contributing to this phenotype." (PMID 39190485, 2024).
meningioma (1 paper, 2022). A generally slow growing tumor attached to the dura mater. "We found that the expression of COL2A1, and COL9A3 were significantly upregulated in meningioma tissues, and the expression of COL14A1, COL4A3, and COL4A2 was significantly down-regulated." (PMID 36538194, 2022).
Multiple renal cysts (1 paper, 2023). The presence of many cysts in the kidney. "Moreover, some reports have shown that COL4A3 and COL4A4 mutations have been detected in patients with multiple renal cysts." (PMID 36981034, 2023).
myopia (1 paper, 2022). "Taken together, scleral Col1a1, Col4a3, Col8a2, Col11a2, and Col15a1 expression were regulated through ER stress during the myopia progression." (PMID 36216837, 2022).
nephromegaly (1 paper, 2024). "Cystic nephromegaly mimicking ADPKD has been reported in patients with COL4A3/COL4A4 variants but in the present series only 3.8% of patients had nephromegaly." (PMID 38317457, 2024).
Obesity (1 paper, 2025). Accumulation of substantial excess body fat. "Furthermore, obesity led to the up-regulation of sodium transporters (Slc13a1, Slc22a8, Slc17a1, Slc17a3) and the down-regulation of structural proteins (Col4a3, Col4a4) as well as Na/K-ATPase subunits encoded by Atp1a1, Atp1b1, suggesting impaired sodium metabolism and underlying renal injury." (PMID 41133844, 2025).
Polypoidal choroidal vasculopathy (1 paper, 2023). The presence of aneurysmal 'polypoidal' lesions in the choroidal vasculature. "Another meta-analysis indicated that Col4a3 was significantly connected with polypoidal choroidal vasculopathy, a subtype of neovascular AMD particularly prevalent in East Asians." (PMID 37025993, 2023).
preeclampsia (1 paper, 2024). Preeclampsia is a hypertensive disorder of pregnancy that is characterized by new-onset hypertension with proteinuria presenting after 20 weeks of gestation, and depending on mild or severe forms may initially present with severe headache, visual disturbances, and hyperreflexia. "A woman with both COL4A3 and COL4A4 pathogenic variants (Patient No. 1446) was diagnosed with preeclampsia while pregnant with her first child at 24 years old and CGN at 29 years old; RRT was initiated at 31 years old." (PMID 38765603, 2024).
pulmonary hypertension (1 paper, 2025). Increased pressure within the pulmonary circulation due to lung or heart disorder. "In the literature has been described that overexpression of anti-angiogenic genes located on chromosome 21—such as COL4A3, endostatin, and RCAN1—is implicated in impaired vascular development and pulmonary hypoplasia, thereby increasing the risk of pulmonary hypertension in DS patients." (PMID 41462807, 2025).
kidney disease (71 papers, 2012 to 2026). "For individuals with kidney disease and heterozygous P/LP variants in the COL4A3/A4 genes, it is advisable to pursue familial co-segregation analysis." (PMID 39673454, 2025). "Newer terms have been used in the literature to denote the kidney disease states linked to pathogenic variants in COL4A3–5 genes." (PMID 39907758, 2025). "The frequent detection of deleterious COL4A3–5 variants in the general population has led to AS being recognized as one of the most common inherited kidney diseases." (PMID 40485705, 2025). "Alport kidney disease (AKD) is a spectrum of kidney disorders caused by pathogenic variants in the α3, α4, and α5 chains of collagen type IV, which are translated from the COL4A3, COL4A4, and COL4A5 genes, respectively." (PMID 39907758, 2025). "In our study, the term AKD was used whenever a P/LP variant in the COL4A3–5 genes was detected in patients exhibiting signs of kidney disease." (PMID 39907758, 2025). "More data on disease risk attributable to heterozygous P/LP autosomal variants in COL4A3/COL4A4 is needed before these are reported to patients undergoing genomic testing for reasons unrelated to evidence of kidney disease." (PMID 39673454, 2025). "The F1 hybrid model of AS with the Col4a3 homozygous mutation develops kidney disease with the first significant increase in renal miR-21 starting at approximately 9 weeks of age, correlated with increased BUN." (PMID 35203245, 2022). "A heterozygous variant in the COL4A3/A4 is associated with a different risk of developing severe kidney disease compared to a hemizygous one in males or even a heterozygous change in the COL4A5 gene in females." (PMID 36553470, 2022). "According to the inclusion and exclusion criteria, our attention was caught by five COL4A3/COL4A4 variants detected in five patients from 343 patients with hereditary kidney diseases." (PMID 35386907, 2022). "Type IV collagen-related nephropathy, in which there is disruption of the normal glomerular basement membrane architecture and kidney disease, has been linked to pathogenic variants in COL4A3, COL4A4, and COL4A59." (PMID 30002862, 2018). "WES identified 2 novel and 2 known pathogenic COL4A3/COL4A4/COL4A5 mutations in 3 families with previously unexplained inherited kidney disease." (PMID 25381091, 2014). "Yet it is important to acknowledge that the risk associated with heterozygosity for a COL4A3/COL4A4 variant in a family known to be affected by severe kidney disease is likely higher than in unselected populations, given the shared genetic and environmental background." (PMID 39673454, 2025). "Pathogenic variants in COL4A3–5 are common causes of inherited kidney disease." (PMID 40485705, 2025). "In addition, the glomerular basement membrane was found to be thinner in patients with a variant in COL4A3/COL4A4 than in patients with other kidney disorders." (PMID 36925663, 2023). "Here, we investigated the differences in cardiorespiratory phenotypes of AS mice with a Col4a3-/- mutation on three different genetic backgrounds, and related changes of blood pressure, renal disease as reflected by increased plasma BUN/creatinine and SGLT2 expression in the kidneys." (PMID 35743114, 2022). "It is noteworthy that although we have found a heterozygous COL4A3 mutation (c.3227 C>T) that may cause extreme deafness and ocular abnormalities, we should continue to monitor possible delayed kidney disease." (PMID 30881523, 2019). "Variations in the genes that encode these α chains—especially COL4A1, COL4A3, COL4A4, and COL4A5—have been associated with several kidney disorders, which involve not only glomerular dysfunction but also the formation of cysts." (PMID 40565535, 2025). "The presence of COL4As (COL4A3, COL4A4, COL4A5) gene variants and other genetic variants associated with kidney disease was examined using a comprehensive gene panel." (PMID 40753325, 2025).